INS (insulin)
Diseases named in the same sentence as INS in open-access papers (continued):
Sharing a sentence is not in itself a finding about the gene and the disease.
type 1 diabetes (continued). "However, Ziegler and colleagues propose dedicated tables for insulin-dependent type 2 diabetes and children/adolescents with type 1 diabetes, possibly resulting in more flexible insulin dosing and the better control of prandial glucose excursions in these groups of patients." (PMID 36900956, 2023). "Moreover, the administration of insulin in type 1 diabetes may elevate ovarian insulin exposure, leading to excessive synthesis of androgen." (PMID 36837921, 2023). "This unique ConA-loaded co-forming matrix may be a promising alternative to current minimally invasive closed-loop insulin delivery systems in type 1 diabetes showing glucose responsiveness, providing sol–gel transitioning for sustaining the release of a short-acting insulin analogue over a period." (PMID 37760986, 2023). "Adjustments in meal-related short-acting insulin both before and after exercise may be advisable for people using degludec, but our data do not provide support for standard insulin degludec dose adjustment after exercise in people with type 1 diabetes." (PMID 36879098, 2023). "Adapted guidelines on insulin discharge medications, which include an example prescription and a discharge medication checklist, have increased doctors' confidence in prescribing discharge medications for individuals who have recently been diagnosed with type 1 diabetes." (PMID 37719599, 2023). "Insulin may play a contributing role, as seen in the association between the first trimester insulin dose in women with type 1 diabetes and birthweight, which is independent of glycaemic control." (PMID 36287249, 2023). "Moreover, the potential clinical relevance of the electrical signals recorded here by MEAs is underscored by the observation that they can be used in an FDA approved simulator of human metabolism of patients afflicted by type 1 diabetes to control in silico glucose homeostasis via insulin delivery." (PMID 37885808, 2023). "Type 1 diabetes (T1D) is a chronic autoimmune disease in which pancreatic beta cells responsible for insulin production are destroyed." (PMID 38371896, 2023). "Type 1 diabetes is thought to consist of an initiation of the immune system attacking, modifying, impairing, and (ultimately) destroying, the insulin-producing beta cells, with the “triggering event” unknown at this time but could include a variety of environmental factors." (PMID 37538198, 2023). "In Australia, access to insulin pump therapy for children with type 1 diabetes (T1D) is predominantly restricted to families with private health insurance." (PMID 37361523, 2023). "Type 1 diabetes (T1D) is characterized by the destruction of insulin-producing β-cells in the pancreas." (PMID 37887145, 2023). "Instances of hypoglycemia (i.e., glucose <70 mg/dL or 3.9 mmol/L) are a common and potentially dangerous complication of type 1 diabetes (T1D) insulin management." (PMID 40303274, 2023). "In type 1 diabetes (T1D), BG regulation is impeded by the autoimmune destruction of insulin-secreting β-cells of the pancreas." (PMID 36791144, 2023). "The safety comparison results from this studies identifies that, CLC insulin delivery was associated with fewer AEs, especially hypoglycemic and hyperglycemic-related events during day and night, than SAP which deems CLC to be an ideal treatment of choice for adolescents with type 1 diabetes." (PMID 37574494, 2023). "Type 1 diabetes (T1D) is characterized by autoimmune-mediated destruction of insulin-secreting pancreatic β-cells." (PMID 37224176, 2023). "Therefore, exogenous insulin is essential for the management of type 1 diabetes." (PMID 37346355, 2023). "However, renal insulin clearance may explain the surprising fact that patients with type 1 diabetes and renal failure may end up with a reduced need for applied insulin." (PMID 37675359, 2023).
type 1 diabetes (continued). "Our understanding of type 1 diabetes (T1D) pathophysiology has advanced significantly in the last 100 years since discovering insulin as a T1D treatment, but additional biomarkers of its earliest stages could help determine its cause and develop more refined and targeted prevention approaches." (PMID 37735622, 2023). "Type 1 diabetes (T1D) results from the complete autoimmune mediated destruction of the insulin producing beta (β) cells within the pancreatic islets." (PMID 37564976, 2023). "Type 1 diabetes (T1D) is a disorder in which the immune system destroys the insulin-producing β cells of the pancreatic islets, resulting in a potentially fatal inability to utilize glucose and numerous co-morbidities from chronic hyperglycemia." (PMID 36817429, 2023). "However, for most children with FH this is their only medical issue, whereas children with type 1 diabetes need to administer/regulate their insulin and perhaps also take other oral medication such as ACE inhibitors, which is a very demanding task during childhood or adolescence." (PMID 38032368, 2023). "Type 1 diabetes mellitus (T1DM) is an autoimmune disease affecting pancreatic islets and, in particular, β-cells, which are responsible for insulin production." (PMID 37048127, 2023). "In children with type 1 diabetes (T1D), insulin pumps and continuous glucose monitoring (CGM) devices can improve glycemic control, decrease rates of severe hypoglycemia and diabetic ketoacidosis, and reduce risk of microvascular complications." (PMID 37294607, 2023). "Type 1 diabetes (T1D or DMT1) is a chronic autoimmune disease resulting in the irreversible destruction of insulin-producing β-cells of the pancreas through autoreactive T cells and hyperglycemia." (PMID 36992490, 2023). "Removing insulin from people with atypical type 1 diabetes (negative autoantibodies) comes with a great risk of ketoacidosis, so careful intervention in a hospital setting is critical when assessing variant carriers and treatment response in paediatric patients." (PMID 37798422, 2023). "An acute ablation of 99% of beta cell mass, (mimicking the Type 1 Diabetes, T1DM model), in adult mice had been shown to induce α cells to transdifferentiate into beta cells to compensate the loss and rescue the need for exogenous insulin for at least 6 months after β cell ablation." (PMID 35198558, 2022). "Focusing on predicting glucose concentration in type 1 diabetes, the Shapley Additive Explanations identified that high values of continuous glucose measurements resulted in high predicted blood glucose levels and that high insulin negatively affected the model output." (PMID 35377325, 2022). "Type 1 diabetes (T1D) is an autoimmune disease in which immune cells infiltrate the islets of Langerhans of the pancreas, ultimately destroy insulin secreting β cells and later lead to overt T1D." (PMID 35937815, 2022). "Furthermore, host responses to the open devices have included invasion by fibroblasts and acellular material, and the demonstration that insulin-producing cells can survive within such devices still falls short of a realistic replacement therapy for type 1 diabetes." (PMID 35104802, 2022). "These include the provision of affordable insulin, access to health care (including glucose monitoring and promptly available services for acute decompensation), and health education (including rapid recognition and detection of type 1 diabetes and ketoacidosis)." (PMID 35143780, 2022). "In addition, the use of insulin in type 1 diabetes might be an important driver of body-weight cycling." (PMID 36397092, 2022). "In addition, LADA is linked to type 1 diabetes-associated loci outside of the HLA region, including PTPN22, INS, and SH2B3 and the associations with PTPN22 and INS appear stronger for LADA with high GADA and for LADA characterized by multiple autoantibodies, respectively." (PMID 35846274, 2022).
type 1 diabetes (continued). "Type 1 diabetes (T1D), also known as insulin dependent diabetes mellitus (IDDM), is mostly an autoimmune diabetes caused by destruction of insulin-producing pancreatic β cell." (PMID 35061693, 2022). "Type 1 diabetes mellitus (T1DM), also known as autoimmune diabetes, is characterized by immune-mediated destruction of pancreatic β cells and insufficiency of insulin secretion in early ages." (PMID 35309368, 2022). "Type 1 diabetes (T1D) results from the T-cell-mediated destruction of insulin-producing β-cells in the pancreas and is the focus of this review." (PMID 35883588, 2022). "However, despite increased use of continuous glucose monitoring (CGM), continuous subcutaneous insulin infusion (CSII) and improved insulin analogues, achieving and maintaining the recommended glucose targets remains challenging for most pregnant women with type 1 diabetes." (PMID 35382796, 2022). "Type 1 diabetes mellitus (T1DM) is an autoimmune disease that results from an immune-mediated destruction of the beta (β) cells of the pancreatic islands, producing insulin." (PMID 36329786, 2022). "The estimated glucose disposal rate (eGDR) is an alternative to the HIEG clamp to assess insulin responsiveness when undergoing type 1 diabetes mellitus (T1DM)." (PMID 36203208, 2022). "Insulin-secreting β cells are selectively destroyed in autoimmune type 1 diabetes (T1D), rendering the body unable to maintain glucose homeostasis." (PMID 35767620, 2022). "Type 1 Diabetes (T1D) is an autoimmune disease that selectively destroys insulin-producing b cells in the pancreas." (PMID 35674842, 2022). "Islet transplantation offers a long-term cure for Type 1 Diabetes (T1D), freeing patients from daily insulin injections." (PMID 36145580, 2022). "Type 1 diabetes (T1D) occurs as a consequence of the autoimmune destruction of insulin-producing pancreatic beta (β) cells and commonly presents with insulin deficiency and unregulated glycemic control." (PMID 36351917, 2022). "In type 1 diabetes mellitus (T1DM), the immune system wrongly destroys β-cells in the pancreas that make insulin; this can occur over a few weeks, months, or years." (PMID 36039251, 2022). "Information on the influence of insulin treatment using advanced hybrid closed loop systems (AHCL) on body weight of young patients with type 1 diabetes (T1D) is scarce." (PMID 36303875, 2022). "Type 1 Diabetes Mellitus (T1DM) is an autoimmune disease, characterized by destruction of insulin producing β cells of Langerhans." (PMID 36741413, 2022). "Type 1 diabetes (T1D) is an auto-immune disease characterized by the progressive destruction of insulin-producing pancreatic beta cells." (PMID 36611907, 2022). "However, in type 1 diabetes, it may be challenging to ascertain whether the level of insulin secretion observed is affected by glucose toxicity or just a function of the remaining functional beta cells." (PMID 35462815, 2022). "Recent years have witnessed rapid advancements in technological devices assisting in insulin delivery and glucose monitoring in type 1 diabetes (T1D) care, with the goal of improving glucose levels to more closely resemble those in people without diabetes." (PMID 36992780, 2022). "Type 1 diabetes (T1D) is a common, chronic, autoimmune disease, characterized by destruction of insulin-producing beta-cells in the pancreas that results in lifelong dependence on exogenous insulin and is associated with a high morbidity and mortality." (PMID 35638288, 2022). "The generated SC-β cells with ZnT8 LOF obtain improved insulin secretion capacity, resist glucotoxicity and lipotoxicity, and show significantly improved glycemic control in diabetic mice, offering an advanced strategy for stem cell-based cell replacement therapy for insulin-dependent diabetes." (PMID 35842441, 2022). "Type 1 diabetes (T1D) is a disease resulting from the autoimmune-mediated destruction of insulin producing β cells of the pancreas." (PMID 36077097, 2022).
type 1 diabetes (continued). "For insulin dependent diabetes, therapy could be painful due to once-daily insulin injection regimen of an intermediate or long-acting insulin, in combination with short-acting (regular) insulin." (PMID 36362870, 2022). "However, insulin therapy alone fails to achieve target glycaemic control in the majority of individuals with type 1 diabetes and is associated with side effects, such as hypoglycaemia and weight gain." (PMID 36671612, 2022). "Instead of using a conventional hypodermic needle that may bring unexpected trypanophobia or pathogenic infections during injection, for example, pre-loaded insulin in such HM could provide a quick and easy-to-use approach to deliver insulin for type 1 diabetes." (PMID 35458358, 2022). "In a study involving the nonobese diabetic (NOD) mice, which spontaneously develop type 1 diabetes at 13-25 weeks due to a mutation that destroys insulin-producing beta cells, tau hyperphosphorylation was significantly increased compared to controls at the S422 epitope." (PMID 34725612, 2021). "Type 1 diabetes mellitus (T1D) is a chronic autoimmune disease in which endogenous insulin production is severely compromised by an immune-mediated injury of pancreatic β-cells." (PMID 34176476, 2021). "Insulin remains the sole therapy for patients with type 1 diabetes (T1D), and despite advances in insulin development, iatrogenic hypoglycaemia remains a common problem for those patients seeking to reach optimal glycemic control." (PMID 33855225, 2021). "Type 1 diabetes (T1D) is an autoimmune disorder in which autoreactive T cells destroy insulin‐producing β‐cells." (PMID 34336205, 2021). "Thus, miR-185-5p might play a role in type 1 diabetes, in which the ability of pancreatic β cells to produce insulin is compromised, and β-cell death is the final and critical step in the development of the disease." (PMID 34335967, 2021). "However, this is with high insulin levels in non-insulin dependent diabetes mellites (NIDDM)." (PMID 34572351, 2021). "Type 1 diabetes (T1D) is a serious metabolic disease characterized by an autoimmune destruction of the insulin-producing β-cells in the pancreas and subsequent insulin deficiency." (PMID 34770425, 2021). "In contrast, other studies concluded a strong correlation of insulin-dependent diabetes and its effect on the function of Leydig cells and testosterone production because of the absence of stimulatory effect of insulin on these cells and an insulin-dependent decrease in FSH." (PMID 34381648, 2021). "Type 1 diabetes mellitus (T1D) is an autoimmune disease characterized by hyperglycemia due to pancreatic β-cell destruction and insulin secretion impairment." (PMID 34172092, 2021). "Importantly, clinical trials have suggested the potential benefits of SGLT2 inhibitors as an adjunctive treatment for type 1 diabetes (T1D), especially in combination with insulin therapy to improve glycemic control in patients with inadequately controlled TID." (PMID 34497852, 2021). "The aim of this study was to evaluate the frequency of hypoglycemia and the treatment satisfaction in patients with type 1 diabetes (T1D) using insulin analogues." (PMID 33905628, 2021). "As an example, we focus on Type 1 diabetes mellitus (T1DM), an autoimmune disease where the autoimmune destruction of the pancreatic beta cells take place, so that insulin synthesis and secretion progressively diminish, up to complete exhaustion." (PMID 34204057, 2021). "Consequently, circulating systemic insulin concentrations in type 1 diabetes patients may lead to relative hyperinsulinemia during and after exercise, promoting excessive glucose uptake and predisposing the patients to hypoglycemia." (PMID 34836420, 2021). "Type 1 diabetes mellitus (T1D) results from the autoimmune-mediated destruction of insulin producing beta cells in the pancreas." (PMID 34305820, 2021).
type 1 diabetes (continued). "In particular, type 1 diabetes (T1D) is a significant burden that typically appears during adolescence and requires life-long insulin administration and blood glucose monitoring." (PMID 34447354, 2021). "Type 1 diabetes mellitus (T1DM) occurs due to an autoimmune disease characterized by the selective destruction of β-pancreatic cells that synthesize and secrete insulin, a hormone responsible for the maintenance of glycemia under physiological conditions." (PMID 34561469, 2021). "Type 1 diabetes is an autoimmune disease caused by selective destruction of β-cells that leads to insulin deficiency and severe hyperglycemia if not treated by daily insulin injections." (PMID 33883217, 2021). "Hence, type 1 diabetes patients need lifelong external insulin treatment." (PMID 34319011, 2021). "Besides, in silico cloning of data from individual type 1 diabetes patients to improve algorithms for closed-loop insulin delivery systems has been reported in 12 and 47 virtual patients in studies that aimed to tackle the challenging problem of inter- and intra-subject variability." (PMID 34803764, 2021). "Type 1 diabetes (T1D), caused by insufficient or no insulin production, is the less common form." (PMID 34305599, 2021). "The physiological glucagon response to hypoglycaemia is often impaired in type 1 diabetes; therefore, addition of glucagon to a closed-loop system confers additional protection from hypoglycaemia and may allow more aggressive insulin delivery to achieve improved glucose control." (PMID 33550442, 2021). "Globally, individuals with autoimmune Type 1 diabetes mellitus (T1DM) continue to depend for survival on insulin injections." (PMID 34710142, 2021). "Type 1 diabetes (T1D) is a chronic autoimmune disease, characterised by progressive destruction and dysfunction of the insulin-producing β cells of the pancreas." (PMID 34876434, 2021). "In type 1 diabetes, taurine exerts its beneficial effects through its antioxidant, anti-inflammatory effects and its effect on increasing glutathione levels, augmenting insulin secretion, activating inhibitory neurotrasmitters and interfering hypothalamic-pituitary-gonadal axis." (PMID 36699147, 2021). "Individuals with type 1 diabetes mellitus (T1DM) face daily hardships due to the rigorous management of insulin replacement therapy, necessary to control blood glucose levels." (PMID 34858339, 2021). "In addition, evidence supporting direct initiation of insulin pump regimens early in the postoperative period, to our knowledge, has not been explored, especially as insulin pumps are rarely initiated at the time of diagnosis for patients with type 1 diabetes." (PMID 34064129, 2021). "Type 1 diabetes (T1D) is an autoimmune disease characterized by the destruction of the insulin-secreting pancreatic beta cells, leading to chronic hyperglycemia." (PMID 34564415, 2021). "We aimed to compare diabetic retinopathy outcomes in people with type 1 diabetes following introduction of continuous subcutaneous insulin infusion (CSII) therapy with outcomes in people receiving continuing therapy with multiple daily insulin injections (MDI)." (PMID 33966091, 2021). "Type 1 diabetes (T1D) is a chronic, incurable autoimmune disorder in which insulin‐producing β cells are destroyed by islet‐infiltrating T cells." (PMID 34336205, 2021). "As we approach the 100-year mark of the discovery of insulin, people with type 1 diabetes may achieve a near normal life expectancy with an overall high quality of life, but this requires tight maintenance of on-target blood glucose levels and good cardiovascular health." (PMID 32533229, 2020). "Type 1 diabetes mellitus (T1DM) is an autoimmune disease in which the insulin-producing beta cells of the pancreas are destroyed by effector lymphocytes sensitized to pancreatic antigens." (PMID 32054009, 2020).